AR (androgen receptor)
Diseases named in the same sentence as AR in open-access papers (continued):
Sharing a sentence is not in itself a finding about the gene and the disease.
prostate carcinoma (continued). "AR plays one of the key roles in the development of prostate cancer, and inhibition of its signalling has been a main therapeutic option to manage locally advanced and metastatic prostate cancer in clinics." (PMID 36429126, 2022). "Prostate cancer is one of the most prevalent malignancies among males, and from existing clinical data, almost all cases are AR-positive tumors." (PMID 35053220, 2022). "These alterations make AR a critical therapeutic target and an ongoing clinical trial is aimed to evaluate a novel AR inhibitor in patients affected by castration-resistant prostate cancer." (PMID 36012138, 2022). "The use of artificial TALENs in prostate cancer cells and androgen receptor (AR) target gene reorganizations are functionally categorized sources of resistance." (PMID 36358785, 2022). "For instance, it has been shown that both VEGF and stromal TGF-β induce AR transactivation under androgen deprivation conditions in the LNCaP prostate cancer cell line." (PMID 35740556, 2022). "The current standard of care for patients with prostate cancer inhibits the AR-signaling axis in tumor cells and will consequently unleash IL1β production." (PMID 36561929, 2022). "Among their compounds, 13 and 14 were conjugated to spirocyclic AR ligands to synthesize AR-degrading PROTACs for the treatment of prostate cancer." (PMID 36235052, 2022). "The ATP2B1 contents of extracellular vesicles are increased in prostate cancer treated with enzalutamide and are negatively regulated by androgen receptor." (PMID 35875160, 2022). "Numerous OAds with AR response elements (AREs) have been developed for evaluation in prostate cancer patients (Sweeney and Halldén, 2016)." (PMID 35813830, 2022). "In DU145 prostate cancer cells, apoptosis and DNA cleavage were induced through the regulation of the androgen receptor (AR)-PI3K/AKT/mTOR-Notch signaling pathway." (PMID 36142874, 2022). "GEO data (GSE2443) were used to compare the expression of AKR1C3 in primary prostate cancer (androgen dependent, Gleasons 5-9, n=10) with that in prostate cancer after androgen ablation (AR-independent, n=10)." (PMID 36591491, 2022). "We tested both tools on the 22Rv1 cell line which is a prostate cancer cell line known for expressing different isoforms of the AR gene." (PMID 35164688, 2022). "PLGA-curcumin NPs enhanced apoptosis and lysosomal activity and deregulated nuclear β-catenin and androgen receptor (AR) activity in prostate cancer cells." (PMID 36144994, 2022). "Competitive binding of antagonists to AR can alleviate the aberrant activation of AR in prostate cancer." (PMID 36015192, 2022). "We focused on mechanisms proximal to the AR, as this nuclear hormone receptor represents the essential driver at different stages of prostate cancer." (PMID 36611998, 2022). "Their research supported the development of an orally active AR PROTAC for the treatment of prostate cancer and provided insights and guidance into the design of orally active PROTACs." (PMID 35702041, 2022). "Treatment of androgen-sensitive prostate cancer cells with an androgen receptor agonist or antagonist revealed that Drp1 is transcriptionally regulated by them." (PMID 35222795, 2022). "FOXA1 can also regulate the transcription and translation of AR genes and increases androgen synthesis, which results in the promotion of prostate cancer cell metastasis." (PMID 35968505, 2022). "During the progression of prostate cancer, androgen receptor (AR) functions as a critical regulator that governs cancer development through transcriptional regulation of its targets gene expression." (PMID 35966880, 2022).
prostate carcinoma (continued). "To investigate the alteration of AR splicing events in TR3-overexpressing prostate cancer cells, we performed next-generation sequencing (NGS) high-throughput RNA-Seq analysis of RNA obtained from TR3-overexpressing and control CWR22Rv1 cells." (PMID 35454821, 2022). "The AR targeted by the anti‐androgen bicalutamide has consistently been reported to promote autophagy in prostate cancer cells." (PMID 36289218, 2022). "The androgen receptor (AR) is a master transcription factor that regulates prostate cancer (PC) development and progression." (PMID 35603787, 2022). "HSP70 binds to the N‐terminal domain of androgen receptor and modulates the receptor function in prostate cancer cells." (PMID 35928554, 2022). "A recent study has shown that DNM1L upregulation by AR signaling in prostate cancer cells affects metabolism and tumorigenesis and its downregulation results in autophagy induction and proliferation inhibition." (PMID 35317831, 2022). "Nowadays, the most common group of therapeutic drugs (i.e., direct approach) used in prostate cancer treatment are AR antagonists (e.g., bicalutamide, nilutamide, or ENZ)." (PMID 36613955, 2022). "Data on prostate cancer tissues have shown that GRP78 expression in AR(+) tumors is significantly higher than in AR(−) tumors." (PMID 35805135, 2022). "AR-dependent transcription promotes O-GlcNAcylation in prostate cancer cells, and, reciprocally, many proteins of the transcription machinery are O-GlcNAcylated." (PMID 35164752, 2022). "Prostate cancer transdifferentiation has been proposed as a mechanism by which tumors acquire treatment resistance to AR targeting agents by reducing dependence on androgen signaling." (PMID 36251389, 2022). "Currently, the PROTACs ARV-471 and ARV-110 are involved in clinical trials for their use as estrogen receptor (breast cancer) degraders and androgen receptor (prostate cancer) degraders, respectively." (PMID 36120561, 2022). "There is a two-way interaction between AR and micro-RNA (miRNA) in prostate cancer; androgens can up-regulate or down-regulate selected miRNAs, and in turn AR itself is a miRNA target." (PMID 36045397, 2022). "We combined immunostaining, bulk RNA sequencing, and single-cell transcriptome sequencing to assess the AR status in prostate cancer with neuroendocrine differentiation." (PMID 36033483, 2022). "LNCaP express the AR and are sensitive to androgen inhibitors, while PC3 cells frequently lack AR entirely, and are a preclinical model of aggressive prostate cancer." (PMID 35447901, 2022). "AR activity (by means of the expression of its target KLK3) was consistently correlated with the expression of GNMT in the majority of prostate cancer datasets analyzed." (PMID 35197445, 2022). "Among these, the miR-27a can act as an oncomiR, inducing increased growth of prostate cancer cells through repression of tumor suppressors, AR control, and prohibitin." (PMID 35456428, 2022). "The aim of our work was to shed further light on a better understanding of AR status in prostate cancer with neuroendocrine differentiation." (PMID 36033483, 2022). "AR transcriptional activity is required for the initiation and progression of prostate cancer and remains critical in metastatic castration-resistant prostate cancer (mCRPC)." (PMID 35550030, 2022). "The CRAC channel inhibitor Diethylstilbestrol (DES), a synthetic ethinyl estrogen, is a possible AR-independent prostate cancer treatment." (PMID 36612099, 2022). "The use of these DNMT inhibitors in pre-clinical studies has been shown to suppress tumour growth, and currently, DNMT inhibitors in combination with chemotherapy, AR inhibitors and immunotherapy are in clinical development for prostate cancer." (PMID 35205419, 2022). "Androgen receptor (AR) and AR signaling are critical in the development and progression of prostate cancer." (PMID 36033483, 2022).
prostate carcinoma (continued). "Inhibition of AR function with AR antagonists such as enzalutamide and apalutamide is a common strategy in the treatment of prostate cancer." (PMID 36536188, 2022). "Prostate cancer (PCa) is a common malignancy among men, in which androgens and the androgen receptor (AR) play key roles in PCa tumorigenesis." (PMID 36248971, 2022). "We then established the 50% effective concentration (EC50) of FL in four prostate cancer cell lines of which two were AR-driven (LNCaP and 22Rv1) and two AR-independent (PC-3 and NCIH660), using viability as the readout." (PMID 35963852, 2022). "Evidence suggests that GATA2 is the family member with an equivalent role in regulating the AR cistrome in prostate cancer." (PMID 35774123, 2022). "Prostate cancer cells treated with an inhibitor of androgen receptor signaling such as enzalutamide can develop resistance by activating the PI3K / Akt signaling pathway, thereby turning on de novo fatty acid synthesis." (PMID 35148308, 2022). "In this review, we summarized the in vivo and in vitro evidence of Tanshinone against prostate cancer and discussed the effect of Tanshinone on nuclear factor kappa-B (NF-κB), AR, and mTOR." (PMID 36080361, 2022). "Many mechanisms of CAF-induced resistance to androgen/AR-directed blockade have been explored in prostate cancer." (PMID 36671452, 2022). "Androgen receptor (AR) signal transduction is crucial for the growth and progression of prostate cancer." (PMID 36359206, 2022). "Combined, these data show that CSA constitutes the majority of CS in prostate cancer and is regulated by AR via CHST11." (PMID 35963852, 2022). "An interesting finding is the fact that agents in clinical development are those targeting the estrogen and androgen receptor in breast and prostate cancer, respectively." (PMID 35249548, 2022). "Our findings show that FcγRIIIa promotes prostate cancer growth and invasion through its direct interaction with androgen receptor." (PMID 34932854, 2022). "More specifically, we have analyzed patients with prostate cancer under treatment with an androgen receptor targeted agent, ovarian cancer receiving treatment with PARP inhibitors and breast cancer patients under treatment with CDK4/6 inhibitors." (PMID 36146552, 2022). "It has been reported that the inhibition of AR signaling promotes CCL2 secretion in prostate cancer cells." (PMID 36077785, 2022). "Recent evidence suggests that NEPC can emerge from pre-existing adenocarcinoma in the advanced stages of prostate cancer progression and develop resistance to AR-targeted therapy." (PMID 36335093, 2022). "This USP22-mediated activation can bypass androgens or AR antagonists (enzalutamide) to induce castration resistance in prostate cancer." (PMID 35935969, 2022). "Conversely, blocking AR signaling in CAFs enabled pro-migratory cytokine release, supporting prostate cancer cell growth and migration." (PMID 36671452, 2022). "The androgen receptor (AR) signaling pathway is critical for growth and differentiation of prostate cancer cells." (PMID 35909568, 2022). "For example, lncRNA CCAT1 acts as the scaffold of DDX5 and androgen receptor transcription complex to promote the expression of androgen receptor-targeted genes, which leads to a poor prognosis for patients with castration-resistant prostate cancer." (PMID 35992805, 2022). "The main goal of this study was to demonstrate if AhR activation by certain indoles can result in the degradation or at least suppression of AR activity in prostate cancer cells." (PMID 36613955, 2022). "The role of AR as a transcription factor in prostate cancer is very well understood, yet in glioma, little is known about it." (PMID 36361793, 2022). "Androgen hormones drive prostate cancer cell proliferation and progression by activating the androgen receptor." (PMID 37255653, 2022).
prostate carcinoma (continued). "Dr. Klocker’s group reported the first study using the ASO technology against the AR gene in 2000, which showed a suppressive effect on prostate cancer LNCaP cell growth." (PMID 35372068, 2022). "Depletion of FKBP52 substantially attenuated cell proliferation in two independent AR‐positive prostate cancer cells, 22Rv1 and LNCaP." (PMID 34057812, 2022). "LSD1 inhibition affected androgen response in prostate cancer and sensitized tumors further to anti-AR therapy." (PMID 35774123, 2022). "Prostate cancer cells are exquisitely dependent on androgens and the androgen receptor (AR) for growth and survival, which explains the efficacy of androgen deprivation therapy (ADT) as a treatment strategy for advanced prostate cancer." (PMID 36923279, 2022). "A consistent finding throughout our study was that MeT exhibited greater potency—in terms of prostate cancer cell growth inhibition, AR DNA binding and transcriptional activity and viral mimicry responses—than DHT." (PMID 36923279, 2022). "Knocking down AR gene expression in prostate cancer cells resulted in profound apoptotic cell death in multiple prostate cancer cell lines, androgen-responsive or castration-resistant." (PMID 35372068, 2022). "Treatment of prostate cancer (PCa) has changed considerably in the last decade due to the introduction of novel androgen receptor (AR)-targeted agents (ARTAs) for patients progressing on androgen deprivation therapy (ADT)." (PMID 35769712, 2022). "ADT impairs androgen receptor (AR) signaling-dependent cell growth in prostate cancer by the reduction of secretory androgen." (PMID 36011028, 2022). "One thing to consider is the possibility of prostate cancer showing androgen receptor-independent growth." (PMID 35681697, 2022). "ABCG2+/AR+ prostate cancer stem cells can survive under castration, chemotherapy, and hypoxia environment." (PMID 35342431, 2022). "ChIP-seq studies have revealed that agonist-liganded AR and antagonist-liganded AR bind to two different motifs, leading to distinct transcriptional outcomes in prostate cancer cells." (PMID 35864113, 2022). "A majority of prostate cancer patients are still receiving primarily or exclusively androgen-receptor (AR)-directed therapies such as androgen deprivation therapy (ADT) or novel antiandrogens including enzalutamide and abiraterone." (PMID 35159068, 2022). "The androgen receptor (AR) signaling is a key contributor to tumorigenesis and the progression of prostate cancer." (PMID 36033483, 2022). "While AR-targeting therapies have become a mainstay in the treatment of prostate cancers, ongoing preclinical and clinical studies in AR+ tumours have demonstrated therapeutic potential for the treatment of AR+ breast cancers using AR antagonists." (PMID 35618789, 2022). "It has been reported that the introduction of GC inhibits the synthesis of AR and ameliorates the symptoms of prostate cancer." (PMID 35184651, 2022). "So, we believe that the transcriptional repressive program of the full‐length wild‐type AR in prostate cancer is determinant for epithelial cell behavior and inhibition of tumor progression." (PMID 34919781, 2022). "In the absence of TLE3, further inhibition of AR led to the derepression of GR expression, which confers resistance to AR-targeted therapy in prostate cancer." (PMID 36438567, 2022). "Intratumoral activation of CYP3A5 in prostate cancer is reported to mediate the growth of prostate cancer cells by facilitating nuclear translocation of AR." (PMID 36359206, 2022). "The interaction of GR with AR is poorly investigated in breast cancer; however, it has been described in adipose tissue, liver, and in prostate cancer." (PMID 35761157, 2022). "Blocking AR nuclear translocation with a potent NLS inhibitor is feasible to suppress prostate cancer development and progression by shutting down AR-modulated gene expression." (PMID 35372068, 2022).
prostate carcinoma (continued). "As androgen receptor (AR) signaling is important for the development of prostate cancer, androgen deprivation therapy (ADT) is a first-line treatment for metastatic prostate cancer (PCa)." (PMID 36077785, 2022). "These are well established oncogenic pathways in prostate cancer, driven by transcription factors AR, MYC and E2F1/2." (PMID 35406480, 2022). "For example, the identification of an androgen receptor (AR) gene through GWAS led to the development of therapeutic drugs for patients with prostate cancer." (PMID 36251695, 2022). "Prostate cancer (PC) is one of the leading lethal malignancies in males, and its development involves androgen receptor (AR) signaling." (PMID 36428807, 2022). "Most interestingly, genomic knock-in of this enhancer region increased the expression level of AR and conferred a castration-resistant state to prostate cancer cells." (PMID 35966880, 2022). "Aberrant activity of the androgen receptor (AR) is central to prostate cancer development and first line therapy for metastatic prostate cancer is androgen deprivation therapy (ADT) which targets AR signalling." (PMID 36171234, 2022). "AR signal pathway is a critical factor in prostate cancer development and progression, and castration-resistant progression is a major obstacle in prostate cancer management." (PMID 36387246, 2022). "First, we set out to determine the interdependencies of AR activation and the NF-κB pathway in the androgen-dependent prostate cancer cell lines VCAP and LNCAPs." (PMID 36551650, 2022). "In the case of taxane research, although the field of prostate cancer clearly identifies androgen receptor signaling as a biological target for taxanes, sex comparisons do not exist, and sex-specific toxicities still remain under-investigated." (PMID 35884386, 2022). "Androgen deprivation, either by interfering with synthesis of testosterone or by blocking androgen receptor (AR) activity with AR antagonists such as bicalutamide or enzalutamide, is still the standard therapy of metastasizing prostate cancer." (PMID 36551650, 2022). "AR is key to normal prostate development as well as oncogenesis of prostate cancer, especially the development of castration‐resistant prostate cancer." (PMID 34057812, 2022). "Among the new CRBN-based PROTACs, PROTAC 2 effectively degraded AR protein with a degradation concentration 50% of 12.5 nM and maximum degradation of 93% in LNCaP prostate cancer cells." (PMID 35702041, 2022). "Following that, we perturbed the system by simulating androgen ablation, as is clinically performed by androgen receptor antagonists to treat metastasizing prostate cancer." (PMID 36551650, 2022). "Metastatic prostate cancers are initially treated with androgen deprivation therapy (ADT) because prostate tissue (benign or malignant) expresses androgen receptor (AR) protein that is critical for prostate cancer development and progression." (PMID 35372068, 2022). "Considering the role of AR in the progression of prostate cancer, we selected the C4-2 PCa cell for further validation." (PMID 36704352, 2022). "Androgen receptor (AR) signaling and DNA repair are tightly interconnected in prostate cancer (PCA)." (PMID 36139600, 2022). "Another study using WB revealed a significant deregulation of transducin beta like related 1 (TBLR1), which is a transcriptional coactivator of androgen receptor (AR) when prostate cancer progresses to CRPC." (PMID 35756667, 2022). "We used the AR/NE scoring gene sets to redefine established prostate cancer cell lines into AR/DN/NEPCs." (PMID 36672609, 2022). "This suggests they are competitive antagonists of AR activity and western blot analysis revealed these PFASs decreased intracellular AR protein in androgen sensitive human prostate cancer cells." (PMID 35093747, 2022). "Ivermectin caused G0/G1 cell cycle arrest, induced cell apoptosis and DNA damage, and decreased androgen receptor (AR) signaling in prostate cancer cells." (PMID 36050295, 2022).